PRPS2 (phosphoribosyl pyrophosphate synthetase 2)
Description:
Catalyzes the synthesis of phosphoribosylpyrophosphate (PRPP) that is essential for nucleotide synthesis.
Synonyms: PRSII
Tractability: Small molecule: a structure with a bound ligand is known. PROTAC: ubiquitination databases record sites on it; its protein half-life has been measured.
Gene: Protein-coding gene on chromosome X (12,791,355 to 12,824,223, forward strand). Ensembl gene ENSG00000101911.
Subcellular location (Human Protein Atlas): Vesicles; Basal body; Nuclear speckles
Pathways (Reactome):
Metabolism: 5-Phosphoribose 1-diphosphate biosynthesis
Gene Ontology:
Molecular function: identical protein binding; protein binding; ribose phosphate diphosphokinase activity; ATP binding; protein homodimerization activity; magnesium ion binding
Biological process: protein hexamerization; purine nucleotide biosynthetic process; 5-phosphoribose 1-diphosphate biosynthetic process; nucleobase-containing compound metabolic process; nucleotide biosynthetic process; pentose-phosphate shunt; ribonucleoside monophosphate biosynthetic process
Cellular component: cytoplasm; cytosol
Homologues: Orthologues: chimpanzee PRPS2 (100% identical), dog PRPS2 (99% identical), rat Prps2 (99% identical), mouse Prps2 (99% identical), tropical clawed frog prps2 (98% identical), guinea pig PRPS2 (98% identical), macaque PRPS2 (92% identical), Drosophila melanogaster Prps (87% identical), pig PRPS2 (87% identical), Caenorhabditis elegans R151.2 (81% identical). Paralogues in human: PRPS1 (95% identical), PRPS1L1 (91% identical), PRPSAP2 (50% identical), PRPSAP1 (49% identical).
Diseases named in the same sentence as PRPS2 in open-access papers:
PRPS2 is named in the same sentence as 35 diseases in open-access papers, as found by Europe PMC text mining. Sharing a sentence is not in itself a finding about the gene and the disease. The quoted sentences say what the papers report.
breast carcinoma (5 papers, 2017 to 2025). "Moreover, overexpression of PRPS2 was strongly associated with poorer patient prognosis across various cancer types, including lung cancer, breast cancer, pancreatic adenocarcinoma, brain lower-grade glioma cancer, mesothelioma, and esophageal carcinoma." (PMID 40295500, 2025). "In a recent study, breast cancer cells undergoing lung metastasis were found to have considerably higher levels of phosphoribosyl pyrophosphate synthase 2 (PRPS2), which is a crucial gene for de novo nucleotide synthesis." (PMID 38434684, 2024). "Tumor stemness can be considerably reduced and lung metastasis can be prevented in breast cancer cells by silencing the PRPS2 gene to block de novo nucleotide synthesis." (PMID 38434684, 2024). "Blocking de novo synthesis by silencing phosphoribosylpyrophosphate synthetase 2 (PRPS2) can effectively decrease the stemness of breast cancer cells and reduce the lung metastasis." (PMID 33186350, 2020). "Our findings found that PRPS2 can regulate nucleotide de novo synthesis to change breast cancer cell stem–like properties in the metastasis, strongly suggesting PRPS2 can be a new specific therapeutic target for breast cancer treatment." (PMID 33186350, 2020). "In our transcriptomics profiling, PRPS2 showed large variation, which suggested its exclusive role in regulating de novo synthesis of breast cancer cells." (PMID 33186350, 2020). "To further assess the significance of nucleotide de novo synthesis for breast cancer metastasis, we specifically silenced Prps2, a key enzyme catalyzing the first reaction in nucleotide synthesis, which was highly up-regulated in metastatic cells." (PMID 33186350, 2020). "Next, we assessed the impact of reduced de novo synthesis on breast cancer metastasis in vivo by injecting Prps2-silenced 4TO7Lung cells or 4T1 cells into the tail vein." (PMID 33186350, 2020). "Furthermore, in a syngeneic mouse breast cancer model using subcutaneously inoculated 4T1 cells, silencing Prps2 dramatically reduced lung metastasis, whereas the growth of the primary tumor was not significantly affected." (PMID 33186350, 2020). "In addition, silencing Prps2 dramatically reduced the expression of stemness signature genes in 4TO7Lung cells, further confirming the pivotal role of Prps2-mediated de novo nucleotide synthesis in the enhancement of CSC-like properties in breast cancer cells." (PMID 33186350, 2020). "Moreover, the expression level of the rate-limiting enzyme PRPS2, which catalyze the PRPP formation, positively correlated with the malignancy of murine and human breast cancer cell lines." (PMID 33186350, 2020).
lymphoma (5 papers, 2016 to 2025). A malignant (clonal) proliferation of B- lymphocytes or T- lymphocytes which involves the lymph nodes, bone marrow and/or extranodal sites. "•PRPS2 loss-of-function induces reductive stress in Myc-driven lymphoma." (PMID 40446642, 2025). "Rather, we demonstrate how inherent differences in PRPS1 and PRPS2 activity can be leveraged to elicit opposing effects on redox homeostasis to selectively target Myc-overexpressing lymphomas with compounds acting on key oxidizing or reducing machineries." (PMID 39868212, 2025). "We chose these enzymes because of the early induction of PRPS2 expression in response to both supraphysiological and normal levels of Myc overexpression and the crucial role of PRPS2 in maintaining lymphoma cell viability." (PMID 39868212, 2025). "In cancer cells, PRPS2 has been reported to be involved in nucleotide metabolism in melanoma and lymphoma and hence is proposed to be a potential therapeutic target for MYC-overexpressing cancers." (PMID 27448979, 2016). "Each compound was tested at increasing concentrations in WT, PRPS1 KO and PRPS2 KO CA46 lymphoma cells such that normalized viability responses could be reported as an EC50 value." (PMID 39868212, 2025). "To test whether differences in allosteric feedback sensitivity to purines account for the phenotypes observed in PRPS2 KO lymphoma cells, we generated ALFA-tagged PRPS1 harboring superactive D52H and H193L mutations to exogenously overexpress in PRPS2 KO cells." (PMID 39868212, 2025). "Employing a pharmacological screen, we demonstrate how targeting PRPS1 or PRPS2 elicits opposing sensitivity or resistance, respectively, to chemotherapeutic agents affecting the thioredoxin and glutathione network, thus providing a therapeutic blueprint for treating MYC-driven lymphomas." (PMID 39868212, 2025). "However, another study confirmed that in c-MYC-overexpressing malignant lymphoma cells, the gene expression of PRPS2 rather than PRPS1 is strongly regulated at the translational level to regulate purine synthesis." (PMID 36203561, 2022). "Mechanistically, we show that genetic inactivation of the PRPS2 isozyme, but not PRPS1, in MYC-driven lymphoma cells leads to elevated NADPH levels and reductive stress-mediated death." (PMID 39868212, 2025). "This phenotype is specific to the Myc-regulated PRPS2 isoform, as knocking out the PRPS1 isoform does not impact viability in these lymphoma cells, suggesting that the Myc-dependent induction of oxidative metabolism may be linked to lymphoma cell viability via PRPS activity." (PMID 39868212, 2025).
neuroblastoma (5 papers, 2016 to 2024). Neuroblastoma (NB) is the most common solid, extracranial childhood tumor. "PRPS2 is associated with Myc driven cancers, such as prostate cancer, neuroblastoma, osteosarcoma." (PMID 37248548, 2023). "Microarray analysis identified genes regulated by both MYCN and TFAP4 in neuroblastoma cells, including Phosphoribosyl-pyrophosphate synthetase-2 (PRPS2) and Syndecan-1 (SDC1), which are involved in cancer cell proliferation and metastasis." (PMID 27448979, 2016). "We therefore chose to first examine the roles of PRPS2 and SDC1 that have been associated with rapid tumor progression and metastasis in certain types of human cancers other than neuroblastoma." (PMID 27448979, 2016). "As we have shown, PRPS1 and PRPS2 have similar amino acid structures and may exhibit similar functions in neuroblastoma cells." (PMID 31443513, 2019). "Finally, we analyzed PRPS2 and SDC1 expression and their association with clinical outcome in the 649 neuroblastoma expression array dataset." (PMID 27448979, 2016). "Our findings that high levels of expression of PRPS2, SDC1 and also SLC7A6 are associated with poor clinical outcome in neuroblastoma, and that PRPS2 and SDC1 are important in proliferation, suggest that these genes may facilitate tumor progression in MYC- and MYCN-driven cancers." (PMID 27448979, 2016). "Kaplan–Meier survival analysis showed that high levels of either PRPS2 or SDC1 expression were strongly associated with poor EFS and OS, suggesting that both these genes may play important roles in MYCN-driven neuroblastoma cell proliferation and tumor progression." (PMID 27448979, 2016). "In particular, we have identified PRPS2 and SDC1 as genes that are positively regulated by both MYCN and TFAP4, and which represent novel candidate therapeutic targets for MYCN-driven neuroblastoma." (PMID 27448979, 2016). "Taken together, these data indicate that both PRPS2 and SDC1 are co-operatively regulated by both MYCN and TFAP4 in neuroblastoma cells." (PMID 27448979, 2016). "However, it is noteworthy that knockdown of PRPS2 suppresses cell proliferation but does not affect cell migration in neuroblastoma." (PMID 38736292, 2024).
lung carcinoma (4 papers, 2024 to 2025). "To validate these clinical observations, we examined endogenous PRPS2 expression in 12 types of human lung cancer cell lines and a normal human lung fibroblast cell line, WI38/VA13." (PMID 40295500, 2025). "Immunohistochemical staining, western blot and reverse transcription‐quantitative polymerase chain reaction (RT‐qPCR) were performed to verify the expression level of PRPS2 in lung cancer." (PMID 38736292, 2024). "Our study investigated the possible molecular mechanism of PRPS2 providing new evidence for the diagnosis and treatment of lung cancer." (PMID 38736292, 2024). "Lung cancer cell lines with stable downregulation of PRPS2 were constructed in A549 cells and NCIH460 cells." (PMID 38736292, 2024). "According to RT‐qPCR and western blot, we also found the increased expression of PRPS2 was in lung cancer tissues." (PMID 38736292, 2024). "Our study confirms that knocking down PRPS2 suppresses the malignancy of lung cancer by blocking cell proliferation and promoting cell apoptosis." (PMID 38736292, 2024). "Next, compared with normal tissues, immunohistochemical (IHC) analysis confirmed that PRPS2 expression in lung cancer tissues was higher." (PMID 38736292, 2024). "Nevertheless, there were still some shortcomings in the study of the role of PRPS2 in lung cancer progression." (PMID 38736292, 2024). "Previous in vitro studies from our group have unveiled the role of PRPS2 in enhancing cisplatin resistance in lung cancer through the promotion of M2 macrophage polarization." (PMID 38952044, 2024). "Phosphoribosyl pyrophosphate synthetase 2 (PRPS2) is known as an oncogene in many types of cancers, including lung cancer." (PMID 38952044, 2024). "PRPS2 knockdown significantly accelerated the apoptosis of lung cancer cells, but inhibited the proliferation, migration and invasion of lung cancer cells in vitro and the growth of transplanted tumors in vivo." (PMID 38736292, 2024). "A previous study has confirmed that PRPS2 is enriched in the exosomes of lung cancer, and the M2 macrophage polarization mediated by exosomes PRPS2 enhances the cisplatin resistance." (PMID 38736292, 2024). "Two isoforms (PRPS1 and PRPS2) in lung cancer cells have a similar enzymatic function." (PMID 37308732, 2024). "The data indicated that low expression of PRPS2 accelerated apoptosis of lung cancer cells." (PMID 38736292, 2024). "Nevertheless, the specific mechanism of PRPS2 on lung cancer cells needs to be further studied." (PMID 38736292, 2024). "Herein, this study first examined the expression of PRPS2 in lung cancer tissues." (PMID 38736292, 2024). "In comparison with normal tissues, PRPS2 was upregulated in lung cancer tissues." (PMID 38736292, 2024). "In addition, the molecular signaling pathways through which PRPS2 is involved in the occurrence and development of lung cancer are still unclear, and further studies are needed." (PMID 38736292, 2024). "In the present article, it was found that the expression of PRPS2 was higher than that of normal tissues, so we speculated that PRPS2 might participate in lung cancer progression." (PMID 38736292, 2024). "The results proved that knocking down PRPS2 restrained the growth of lung cancer tumors in vivo." (PMID 38736292, 2024). "Therefore, PRPS2 knockdown retards lung cancer progression by inhibiting cell migration and invasion." (PMID 38736292, 2024). "According to TCGA, mRNA levels of PRPS2 in lung cancer were clearly higher than in normal tissues." (PMID 38736292, 2024). "Next, A549, and NCIH460 cells were selected to silence PRPS2 expression by RNA interference technology, aiming to explore the function of PRPS2 in the invasion, proliferation, migration, apoptosis and in vivo growth of lung cancer cells." (PMID 38736292, 2024). "In lung cancer, PRPS2 silencing suppressed the malignant progression, indicating that PRPS2 might be a novel biomarker for lung cancer treatment and diagnosis." (PMID 38736292, 2024).
lung carcinoma (continued). "Here, the results suggested that PRPS2 may be involved in the malignant progression of lung cancer." (PMID 38736292, 2024). "Herein, we aimed to shed light on the roles of PRPS2 in regulating the recruitment of TAM and MDSC, while also investigating the potential interplay between PRPS2 and CCL2 in the context of lung cancer." (PMID 38952044, 2024).
melanoma (4 papers, 2016 to 2024). A malignant, usually aggressive tumor composed of atypical, neoplastic melanocytes. "In melanoma, PRPS2 has been shown to be a direct target of c‐Myc, and knocking down PRPS2 leads to a reduction of dNTP and delays cell cycle progression." (PMID 38736292, 2024). "PRPS2 functions in the deoxynucleotide synthesis pathway, and its overexpression stimulates the proliferation and metastatic capacity of melanoma cells." (PMID 37511580, 2023).
B cell lymphoma (3 papers, 2015 to 2025). "Depletion of PRPS2 levels by siRNA in c-MYC-driven B-cell lymphomas improved survival and induced complete tumor regression in 30 % of mice, strongly indicating that protein and nucleotide biosynthesis controlled by PRPS2 is crucial for c-MYC-driven tumorigenesis." (PMID 26654227, 2015). "To assess the requirement of Myc-driven, PRPS-dependent redox regulation in the context of fully transformed B cell lymphoma, we generated single-cell selected CRISPR/Cas9 knockouts of both PRPS1 and PRPS2 in CA46 and DG75 Burkitt’s lymphoma-derived cell lines." (PMID 39868212, 2025).
non-small cell lung carcinoma (3 papers, 2024 to 2026). A group of at least three distinct histological types of lung cancer, including non-small cell squamous cell carcinoma, adenocarcinoma, and large cell carcinoma. "For instance, the enriched PRPS2 in the exosomes of non-small-cell lung carcinoma (NSCLC) cells mediates the polarization of M2 macrophages to promote the cisplatin resistance of non-small-cell lung cancer (NSCLC) cells." (PMID 39061140, 2024). "Examples include exosomes secreted by non-small cell lung cancer, which are rich in miR-21, LINC00313, and PRPS2, promoting M2 polarization in macrophages." (PMID 38655063, 2024).
colorectal cancer (2 papers, 2022 to 2024). A primary or metastatic malignant neoplasm that affects the colon or rectum. "Human PRPS1 and PRPS2 gene products are implicated in drug resistance associated with recurrent acute lymphoblastic leukaemia and progression of colorectal cancer and hepatocellular carcinoma." (PMID 35741038, 2022). "Similar findings showed that the metastasis ability of colorectal cancer cells was enhanced after PRPS2 overexpression." (PMID 38736292, 2024). "It has been observed that PRPS1 is expressed constitutively, whereas PRPS2 is expressed inter alia in colorectal cancer (CRC) metastasis and hepatocellular carcinoma (HCC)." (PMID 35741038, 2022).
glioma (2 papers, 2022 to 2024). A benign or malignant brain and spinal cord tumor that arises from glial cells (astrocytes, oligodendrocytes, ependymal cells). "Endoplasmic reticulum-induced stress via tunicamycin in glioma cells, together with the suppression of ERN1, downregulates PRPS1 and PRPS2 gene expression levels." (PMID 35741038, 2022). "Furthermore, we found that six downregulated genes, including pLCE1, PRPS2, FH, ASL, DTYMK, and CTPS1 were significantly increased in high-grade glioma tissues (p < 0.001)." (PMID 38438374, 2024). "Furthermore, the expression of PRPS1, PRPS2, PRPSAP1 (PAP39) and PRPSAP2 (PAP41) genes in U87 glioma cells is not inhibited by ERN1 (EC 2.7.11, endoribonuclease activity of endoplasmic reticulum to nuclei-1)." (PMID 35741038, 2022).
male infertility (2 papers, 2022 to 2023). The inability of the male to effect fertilization of an ovum after a specified period of unprotected intercourse. "In addition, PRPS2 is associated with low spermatogenesis and Sertoli cell-only syndrome (SCOS), which may be a potential biomarker and therapy target of male infertility." (PMID 37248548, 2023). "However, a recent publication has correlated the depletion of murine PRPS2 by sh RNA lentivirus with hypospermatogenesis, suggesting that PRPS2 may be a potential biomarker for male infertility." (PMID 35741038, 2022).
prostate adenocarcinoma (2 papers, 2020 to 2024). "We found that PRPS2 was dramatically upregulated in prostate adenocarcinoma tissues in comparison with normal tissues, and that increased PRPS2 was linked intimately to advanced clinical stage and pT status." (PMID 31956349, 2020). "Furthermore, the expression level of PRPS2 in prostate adenocarcinoma is sharply increased, and knocking down PRPS2 significantly promotes cell apoptosis and blocked cell multiplication." (PMID 38736292, 2024).
Sertoli Cell-Only Syndrome (2 papers, 2020 to 2023). A type of male infertility in which no germ cells are visible in any of the biopsied SEMINIFEROUS TUBULES (type I) or in which germ cells are present in a minority of tubules (type II). "Notably, our previous study revealed that the expression of PRPS2 correlated with sertoli-cell only syndrome via inhibits cell apoptosis." (PMID 31956349, 2020).
acute lymphoblastic leukaemia (1 paper, 2022). "Human PRPS1 and PRPS2 have been identified in acute lymphoblastic leukaemia (ALL) as the major cause of drug resistance to the prodrugs thioguanine and thiopurine, which are used in cancer therapy." (PMID 35741038, 2022).
Ataxia (1 paper, 2019). Ataxia refers to impaired coordination of voluntary muscle movement. "PRPPS (Prps1, Prps1l1, Prps2) was previously reported to be affected by amino acid depletion, while mutations in Prps1 have been associated with hyperuricemia, hyperuricosuria, hypotonia, and ataxia and gain-of-function mutation results in PRS-1 superactivity." (PMID 31285465, 2019).
cervical cancer (1 paper, 2024). A primary or metastatic malignant neoplasm involving the cervix. "Likewise, in cervical cancer, PRPS2 silencing repressed the invasion and migration." (PMID 38736292, 2024).
infantile-onset epilepsy (1 paper, 2021). Epilepsy starting in the first 12 months of life, including self-limiting and refractory seizures, and epilepsies with and without developmental disorders. "In the chronic stage of infantile-onset epilepsy, DIANA-mirPath identified two gene targets of miR-451-5p (Prps2—Phosphoribosyl Pyrophosphate Synthetase 2 and Gfpt2—Glutamine-Fructose-6-Phosphate Transaminase 2) involved in multiple metabolic pathways." (PMID 33958654, 2021).